ENSG00000239093
Synonyms: LOC124905594
Gene: Small nucleolar RNA gene on chromosome 3 (187,423,315 to 187,423,419, forward strand). Ensembl gene ENSG00000239093.
Gene Ontology:
Biological process: RNA processing
Cellular component: nucleolus
Homologues: Paralogues in human: SNORD13D (88% identical), SNORD13E (88% identical), SNORD13 (87% identical), SNORD13P3 (85% identical), SNORD13P1 (81% identical).